CEBPB (CCAAT enhancer binding protein beta)
Diseases named in the same sentence as CEBPB in open-access papers (continued):
Sharing a sentence is not in itself a finding about the gene and the disease.
metabolic disease (6 papers, 2019 to 2023). A congenital disorder (due to inherited enzyme abnormality) or acquired (due to failure of a metabolically important organ) disorder resulting from an abnormal metabolic process. "Based on the pseudo-temporal continuum profile, we identified the TF (ALX4, HINFP, CEBPA, CEBPB, DMBX1, MLXIPL, ONECUT1, and RBPJL) and depicted the regulated kernel genes co-networks, which were subjected to the metabolism disorders." (PMID 33462196, 2021).
adenocarcinoma (4 papers, 2013 to 2026). A common cancer characterized by the presence of malignant glandular cells. "While C/EBPβ was expressed in human adenocarcinoma cell lines, neither overexpression of nuclear C/EBPβ nor knockdown of CEBPB had significant effect on cell proliferation." (PMID 25767874, 2015).
mental illness (3 papers, 2019 to 2025). "Therefore, we solidly demonstrated that a significantly increased CEBPB that recognizes the HTR1A strongly inhibited the level of this gene and leaded to the susceptibility to the mental illness." (PMID 31614865, 2019).
connective tissue disorder (1 paper, 2015). A disease involving the connective tissue. "We also find evidence for activation of multiple other inflammatory and connective tissue-disorder pathways mediated through pro-inflammatory TF genes such as STAT3, IRF1 and IRF7, CEBPB and SMAD4." (PMID 26202100, 2015).
heart disease (1 paper, 2020). "Therefore, whether CEBPβ is a feasible target for treating heart disease needs further in-depth examination." (PMID 32223896, 2020).
CEBPB also shares sentences with these, for which no sentence is quoted: Cognitive impairment (17 papers); lung fibrosis (14); liver fibrosis (10); bacterial infection (7); rheumatoid arthritis (7); liver cancer (6); renal fibrosis (6); asthma (5); fibrosis (5); liver inflammation (5); skin tumors (5); type 2 diabetes (5); acute promyelocytic leukemia (4); breast tumor (4); cardiovascular diseases (4); chronic myeloid leukemia (4); Infertility (4); Arthritis (3); breast invasive carcinoma (3); diabetic cardiomyopathy (3); endothelial dysfunction (3); hepatitis (3); hyperlipidemia (3); injury (3); Lewis lung carcinoma (3); myeloid tumor (3); neurological disorders (3); nonalcoholic steatohepatitis (3); serous ovarian cancer (3); skin carcinoma (3).
A further 160 diseases each share a sentence with CEBPB in 3 papers or fewer.